RNU6-652P (RNA, U6 small nuclear 652, pseudogene)
Gene: Small nuclear RNA gene on chromosome 4 (55,885,595 to 55,885,701, forward strand). Ensembl gene ENSG00000202358.
Homologues: Orthologues: chimpanzee U6 (97% identical), macaque U6 (89% identical), mouse Gm23629 (84% identical), guinea pig U6 (83% identical). Paralogues in human: RNU6-1020P (86% identical), RNU6-238P (86% identical), RNU6-24P (85% identical), RNU6-43P (85% identical), RNU6-727P (85% identical), RNU6-820P (85% identical), RNU6-668P (84% identical), RNU6-774P (84% identical), RNU6-1011P (83% identical), RNU6-1094P (83% identical), RNU6-1131P (83% identical), RNU6-11P (83% identical), and 1289 more.